AHR (aryl hydrocarbon receptor)
Diseases named in the same sentence as AHR in open-access papers (continued):
Sharing a sentence is not in itself a finding about the gene and the disease.
melanoma (continued). "We have recently reported that stable AhR knockdown in B16F10 mouse melanoma cells enhanced their primary tumorigenicity and their metastatic potential to the lungs, whereas constitutive AhR activation strongly blocked melanoma progression." (PMID 27243009, 2016). "In human melanoma, AhR regulates aldehyde dehydrogenase to block melanoma tumorigenesis and metastasis." (PMID 27243009, 2016). "In B16F10 mouse melanoma cells, stable knockdown of AhR enhanced tumorigenesis and metastatic potential to the lungs, while constitutive AhR activation potently inhibited melanoma progression." (PMID 27669218, 2016). "We have shown that stable AhR knockdown (sh-AhR) increases primary tumorigenesis and lung metastasis of mouse melanoma cells and that AhR expression was reduced in advanced human melanomas." (PMID 26242870, 2015). "Mouse melanoma B16F10 cells were engineered by retroviral transduction to stably downregulate AhR expression, Aldh1a1 expression or both." (PMID 26242870, 2015). "Confocal microscopy analyses of matrigel-coated culture transwells showed that sh-AhR + sh-Aldh1a1 cells had a significant impairment to invade as compared to sh-AhR melanoma cells." (PMID 26242870, 2015). "We have attempted to determine Aldh1a1 levels by immunohistochemistry in our tissue microarrays (TMA) containing human melanomas expressing different amounts of AHR." (PMID 26242870, 2015). "In this study, we have found that Aldh1a1 upregulation is likely an intermediate factor promoting melanoma growth and metastasis in AhR depleted cells." (PMID 26242870, 2015). "?A3B2 tlsb=-.15pt?>The inverse correlation between AhR and Aldh1a1 in mouse melanoma cells was also observed in human melanoma cells previously reported to express high (A375) or low (C8161) receptor levels." (PMID 26242870, 2015). "The increased tumorigenic potential of sh-AhR melanoma cells correlated with higher levels of cancer stem-like markers, suggesting a more undifferentiated status." (PMID 26242870, 2015). "In summary, we present evidences for the existence of a regulatory mechanism by which AhR modulates Aldh1a1 expression and activity in melanoma cells." (PMID 26242870, 2015). "AhR knockdown in mouse melanoma B16F10 cells significantly increased Aldh1a1 mRNA and protein expression as compared to wild type B16F10 cells." (PMID 26242870, 2015). "AhR knockdown increased melanoma cell migration and invasion and the expression of mesenchymal markers α-smooth muscle actin and Snail." (PMID 26242870, 2015). "The results presented here, propose the existence of regulatory pathway between AhR and Aldh1a1 in melanoma considering that the pro-tumorigenic effects of Aldh1a1 overexpression were significantly augmented in an AhR deficient background." (PMID 26242870, 2015). "AhR mediates growth inhibition of melanoma cells by the therapeutic drug leflunomide, whereas constitutive AhR activation repressed melanoma growth and metastasis." (PMID 26242870, 2015). "Aldh1a1 and AhR converge at the control of the cancer stem-like phenotype in melanoma cells, although with an opposite pattern that resembles that found for tumor growth." (PMID 26242870, 2015). "Consistently, human melanoma cells and biopsies from melanoma patients had reduced AhR expression as compared to bening nevi." (PMID 26242870, 2015). "We have shown that AhR knockdown promotes melanoma primary tumorigenesis and lung metastasis in the mouse and that human metastatic melanomas had reduced AhR levels with respect to benign nevi." (PMID 26242870, 2015). "To further analyze the effects of Aldh1a1 in the metastatic burden of melanoma cells, we used retroviral transduction to produce sh-AhR-Luc and sh-AhR + sh-Aldh1a1-Luc cells expressing the in vivo marker luciferase." (PMID 26242870, 2015). "Our results reveal that the AhR is a molecular target of leflunomide and support the feasibility of the clinical application of leflunomide for treating melanoma." (PMID 22815870, 2012).
melanoma (continued). "We first evaluated the expression of AhR in melanoma cells and found that AhR is highly expressed in A375 melanoma as well as in several other cancer cell types." (PMID 22815870, 2012). "In the present study, we identified an AhR-dependent inhibition of proliferation of A375 melanoma cells by the clinically-used drug leflunomide, which has been reported previously to activate the AhR." (PMID 22815870, 2012). "Researchers utilized patient-derived xenografts transplanted into in vivo mouse models to discover that the Aryl hydrocarbon Receptor (AhR), a transcription factor, becomes constitutively activated in these resistant melanoma cells, thereby driving treatment resistance." (PMID 41463545, 2025). "Melanoma samples from The Cancer Genome Atlas (TCGA) and normal skin tissues from the Genotype-Tissue Expression (GTEx) database were analyzed to identify differentially expressed genes, which were intersected with a curated list of AhR-related pathway genes." (PMID 39835132, 2024). "However, we also note a possible dual role of AhR in melanoma natural history, including its protective and protumor roles." (PMID 38927967, 2024). "However, the specific downstream targets and mechanisms by which AhR influences melanoma remain insufficiently understood." (PMID 39835132, 2024). "Several studies imply a tumor regulatory role for AhR in melanoma." (PMID 38807762, 2024). "Despite its role as an oncogene, AHR also acts as a tumour suppressor in several types of cancer, such as those affecting the brain and central nervous system, liver, digestive system, skin (melanoma), and reproductive system." (PMID 37760608, 2023). "Recently developed AHR antagonist has shown efficacy in melanoma and could potentially have an impact on the platinum-resistant NSCLC." (PMID 37226257, 2023). "AhR is actively involved in the metastatic spread of melanoma cells." (PMID 37830596, 2023). "In addition, numerous studies have demonstrated increased expression of AHR in various cancer subtypes, including chronic lymphocytic leukaemia, melanoma, breast cancer brain cancer and pancreatic cancer." (PMID 37760608, 2023). "Next, given prior reports that AhR activation induces MMP2 in melanoma, we evaluated whether it might correlate with Mmp2 expression in these skin samples." (PMID 35316219, 2022). "In melanoma cells, the activation of AHR promotes TNFα-dependent inflammation and metastasis." (PMID 36292946, 2022). "In addition to their roles in sensitizing melanoma cells to BRAFi, the SRC inhibitors Bos and Das, even at low doses (1 μM), prevented the invasive capacity of wild‐type AhR melanoma cells (red) in three‐dimensional spheroid assays." (PMID 36305167, 2022). "Therefore, the authors proposed the weakening of AhR action as a strategy to address BRAFi resistance and recurrence in melanoma." (PMID 35458697, 2022). "In addition, IDO1/TDO activation causes kynurenine (Kyn) accumulation in the TME, which activates the aryl hydrocarbon receptor (AhR), orienting T-cell differentiation into FoxP3+ regulatory T cells and the resultant melanoma immune escape." (PMID 36003368, 2022). "First, high level and activity of AhR mediates the invasive/dedifferentiated phenotype of melanoma through the direct regulation of the expression of many genes involved in invasion (COL1A1, COL6A1, COL6A2, CYR61, STC2...) and dedifferentiation phenotypes (CCL2, NTM, NUAK2, SOX9, ABCG2...)." (PMID 36305167, 2022). "Furthermore, activation of AhR appears to favor the maintenance of melanoma by increasing the density of programmed cell death protein 1 (PD-1) in tumor-infiltrating T cells surrounding melanoma, resulting in cancer cells escaping the immune response." (PMID 35458697, 2022). "Thus, both AhR expression and its activation control the phenotype of melanoma cells and their sensitivity to BRAFi." (PMID 36305167, 2022).
melanoma (continued). "In this context, AhR may antagonize the pro-tumoral effects of Aldh1a1; thus, an AhRlow/Aldh1a1high phenotype could be indicative of a poor outcome in melanoma." (PMID 33451095, 2021). "In addition, the selective blockade of AhR reduced the tumour growth of mouse models of IDO-expressing melanoma." (PMID 34944851, 2021). "Moreover, in the inflammatory environment, FICZ-mediated AhR activation induces the phenotypic switch of melanoma cells into the dedifferentiated state." (PMID 33499346, 2021). "Silencing of AhR suppressed the growth of NRAS-mutant melanoma cells expressing high levels of AhR." (PMID 33451095, 2021). "To address whether the IDO/TDO-Kyn-AHR axis limits the efficacy of immune-based therapies, we examined an RNAseq dataset of tumors from 68 patients with advanced melanoma before and after anti-PD-1 therapy." (PMID 32782249, 2020). "Conversely, high canonical AhR activity mediates drug resistance through the activation of a dedifferentiated cell state, suggesting AhR transcription factors as additional drivers of melanoma relapse." (PMID 32466585, 2020). "Here, we focused on the role of a set of flavonoids in the control of the transcriptional activity of AhR in the context of cutaneous melanoma, some of which have shown to inhibit the development, growth, and spreading of melanoma through their antioxidant properties." (PMID 32708687, 2020). "Furthermore, blockade of AHR signaling enhances anti-programmed cell death protein 1 (αPD-1) therapy effects in a myeloid-dependent manner in a B16 melanoma model." (PMID 33171762, 2020). "Interestingly, all tested compounds in higher concentrations decreased the protein level of AhR in both melanoma cell lines." (PMID 33114713, 2020). "Moreover, a direct interaction of AHR with the BRAF inhibitor vemurafenib has been described in melanoma cells as well as in T cells and keratinocytes." (PMID 31795255, 2019). "Activation of AHR conveyed melanoma cells with resistance to BRAF inhibitors." (PMID 31795255, 2019). "In addition, some reports using melanoma cell lines indicate that AHR activation attenuates tumorigenicity; in contrast, others reported that AHR activation promotes tumorigenicity of melanoma." (PMID 31552251, 2019). "Accordingly, inhibition of AHR sensitized melanoma cells to targeted therapy." (PMID 31795255, 2019). "Gene expression analyses revealed that AHR is highly expressed in some melanoma cell lines." (PMID 31795255, 2019). "In addition, they also reported that co-administration of AHR antagonists with BRAF inhibitors maintains at least partial sensitivity to BRAF inhibitors in melanoma cells." (PMID 31552251, 2019). "We thus propose AhR-impairment as a strategy to overcome melanoma resistance." (PMID 30429474, 2018). "The AGR3/AHR posterior probability for shared genetic effects between tanning ability and CMM was 1, thus indicating that the same genetic variants are involved in both decreased tanning ability and increased risk of melanoma." (PMID 29739929, 2018). "Considering AhR-activation modulates the pigmentation program in melanoma cells, we investigated whether the AhR gene expression program is connected to BRAFi resistance." (PMID 30429474, 2018). "Interestingly, AhR knockdown increased melanoma cell migration and invasion and the expression of mesenchymal markers α-smooth muscle actin (α-SMA) and Snail." (PMID 27243009, 2016). "The main findings from this study are that AhR expression restrains Aldh1a1 activity in murine melanoma cells and that, as a consequence, AhR depletion results in Aldh1a1 upregulation and in the exacerbation of melanoma primary tumorigenesis and metastasis in vivo." (PMID 26242870, 2015). "Since AhR negatively modulate Aldh1a1 activity, melanoma tumors could restrict AhR expression in order to maintain the tumor promoting activity of Aldh1a1." (PMID 26242870, 2015).
melanoma (continued). "Indeed, Aldh1a1 downmodulation markedly reduced the number of cancer stem-like cells and impaired primary tumorigenesis and lung metastasis in AhR depleted melanoma cells." (PMID 26242870, 2015). "Since AhR expression appears to be reduced in advanced human melanomas, it will be interesting to investigate whether Aldh1a1 becomes upregulated in the same tumors and if it contributes to disease progression." (PMID 26242870, 2015). "We then hypothesized that the increased tumorigenic and metastatic potential of sh-AhR melanoma cells could depend, at least in part, to their high Aldh1a1 activity." (PMID 26242870, 2015). "The evidences showing that Sox2 expression was coincident with Aldh1a1 overactivation, and that Sox2 expression inhibited Aldh1a1 in AhR knockdown cells, suggest the existence of a coordinated pathway involving AhR-Aldh1a1-Sox2 in the regulation of stemness in melanoma cells." (PMID 26242870, 2015). "In this work, we have investigated the Aldh1a1 enzyme as a molecular intermediate whose upregulation in AhR depleted cells could promote melanoma progression." (PMID 26242870, 2015). "We therefore suggest that AhR may block melanoma by inhibiting the pro-tumoral effects of Aldh1a1, and that coordinated expression of AhR and Aldh1a1 could be a useful molecular marker in melanoma." (PMID 26242870, 2015). "The functional interaction between Aldh1a1 and AhR could be also relevant for the control of migration and invasion of melanoma cells." (PMID 26242870, 2015). "Indeed, we have recently reported that stable AhR knockdown in B16F10 melanoma cells enhanced their tumorigenicity and their metastatic potential to the lungs whereas constitutive AhR activation strongly blocked melanoma progression." (PMID 26242870, 2015). "Since AhR may antagonize the protumoral effects of Aldh1a1, the AhRlow-Aldh1a1high phenotype could be indicative of bad outcome in melanoma." (PMID 26242870, 2015). "AhR has a role in melanoma primary tumorigenesis and lung metastasis." (PMID 26242870, 2015). "We suggest that the coordinated expression of AhR and Aldh1a1 could be a useful molecular marker in melanoma." (PMID 26242870, 2015). "We therefore tested whether the AhR regulates the anti-proliferative effects of leflunomide in melanoma." (PMID 22815870, 2012). "We first confirmed the expression of AhR in A375 melanoma cells by Western blot." (PMID 22815870, 2012). "In the present study, we hypothesized that the effects of leflunomide in A375 melanoma cells are mediated by a previously unappreciated activation of the AhR." (PMID 22815870, 2012). "Our hypothesis is also further reinforced by published reports in BRAFV600E melanoma that showed activation of the SRC pathway by Aryl hydrocarbon Receptor (AhR) promotes the acquisition of an invasive and aggressive phenotype resistant to front-line BRAF inhibitors." (PMID 40481178, 2025). "Standard chemotherapeutic drugs may promote immune evasion by activating the KP; in HNSCC cells, cetuximab induces IDO1, and in melanoma, the anti‐PD1 monoclonal antibody (mAb) nivolumab can induce IL4I1 and IDO1, with nivolumab treatment linked to AhR activation." (PMID 40103267, 2025). "Additionally, AhR has been shown to modulate the effectiveness of therapeutic agents for melanoma." (PMID 35683027, 2022). "Activation of AhR triggers the expression of gene resistance to inhibitors of the mutant proto-oncogene V600 B-Raf and serine-threonine kinase in melanoma, and an increase in the expression of apoptosis protein 1 (PD-1) in T cells infiltrating tumors that surround the melanoma." (PMID 35683027, 2022). "Indeed, AHR diminishes the efficacy of novel immunotherapies by potentiation of the production of antibodies that block immunoregulatory molecules and by suppressing apoptosis of dormant melanoma cells." (PMID 33806305, 2021). "Moreover, activation of AHR was reported to promote resistance to BRAF inhibitors in melanoma." (PMID 32767816, 2021).
melanoma (continued). "Moreover, AhR protein level is reduced in human melanomas with respect to nevi lesions." (PMID 33499346, 2021). "Furthermore, this study also suggested that targeting AhR signaling could prevent the induction of the BRAF inhibitor resistance gene in melanoma cells, thus augmenting the efficacy of BRAF inhibitors." (PMID 31514399, 2019). "AHR activation induces the expression of resistance genes against the inhibitors of V600E mutated B-Raf proto-oncogene, serine/threonine kinase (BRAF) in melanoma and upregulation of programmed cell death protein 1 (PD-1) in tumor-infiltrating T cells surrounding melanoma." (PMID 31552251, 2019). "Furthermore, AHR modulates the efficacy of key therapeutic agents in melanoma." (PMID 31552251, 2019). "Combining CAI with IDO1/AhR inhibitors could lead to a more selective anti-tumor immunoreaction, which was confirmed in a specialized coculture system consisting of B16 melanoma cells expressing ovalbumin (OVA) antigen (B16-OVA) and OVA-specific CTLs derived from OT-1 transgenic mice." (PMID 31511064, 2019). "Therefore, the functional interaction between AhR and Aldh1a1 could be of potential interest for melanoma progression and therapy." (PMID 26242870, 2015). "Therefore, the tumor suppresor role of AhR in melanoma could take place by antagonizing the Aldh1a1 activity." (PMID 26242870, 2015). "Thus, AhR and Aldh1a1 had opposite expression patterns in both murine and human melanoma cells." (PMID 26242870, 2015). "The upregulation of AHR, MAP2K1, and PRKACB, alongside the downregulation of KLF5 and PIK3R2, suggests that these genes play critical roles in melanoma progression through various signaling pathways." (PMID 39835132, 2024). "Blockade with the AhR antagonist 3′,4′-dimethoxyflavone impaired tumor growth and improved survival in B16GF10 melanoma." (PMID 38339226, 2024). "Interestingly, the phenotype of melanoma cells lacking Mitf transcription factor was similar to those observed while AhR is highly expressed and activated, allowing to consider a new balance between these two transcription factors for the control of melanoma plasticity." (PMID 36305167, 2022). "Together, AhR‐dependent transcriptional reprogramming and SRC activation triggers the cell plasticity of BRAFi‐resistant melanoma." (PMID 36305167, 2022). "Interestingly, AhR may play the role of tumor suppressor in melanoma." (PMID 34299117, 2021). "When studying IL4I1 levels in ICB-treated advanced melanoma patients, it was noted that nivolumab therapy correlated with the induction of both IL4I1 and IDO1 and resulted in AhR activation." (PMID 34944851, 2021). "An AhR antagonist, such as resveratrol, increased BRAFi sensitivity and delayed relapses in PDX melanoma." (PMID 33451095, 2021). "The same treatment regimen of IDO1/AhR inhibitor with IFNγ reduced tumor growth and prolonged the overall survival of NOD/SCID mice bearing B16 melanoma tumors." (PMID 33379189, 2020). "Recent studies indicate that AHR inhibition might be a suitable strategy to enhance the efficacy of immunotherapeutic applications against malignant melanoma and, in addition, AHR modulation may affect melanoma resistance against protein kinase inhibitors frequently used in the clinical routine." (PMID 31795255, 2019). "Taken together, these data underscore the importance of the AHR system in carcinogenesis and maintenance of skin cancers, especially SCC and melanoma." (PMID 31552251, 2019). "In the following, we, therefore, focus on environmentally induced AHR signaling and its relevance for the development and progression of SCC and malignant melanoma." (PMID 31795255, 2019). "As anticipated from former TCGA results and recent studies, melanoma samples naive of any treatment (CTR) are characterized by an elevated intra- and inter-tumoral heterogeneity in terms of differentiation states and AhR signatures." (PMID 30429474, 2018).